BAD (BCL2 associated agonist of cell death)
Description:
Promotes cell death. Successfully competes for the binding to Bcl-X(L), Bcl-2 and Bcl-W, thereby affecting the level of heterodimerization of these proteins with BAX. Can reverse the death repressor activity of Bcl-X(L), but not that of Bcl-2 (By similarity). Appears to act as a link between growth factor receptor signaling and the apoptotic pathways.
Synonyms: BCL2L8; BBC2
Tractability: Small molecule: a high-quality ligand is known; it belongs to a druggable protein family. PROTAC: its protein half-life has been measured; a small molecule that binds it is known.
Target class: Other cytosolic protein
Gene: Protein-coding gene on chromosome 11 (64,269,828 to 64,291,946, reverse strand). Ensembl gene ENSG00000002330.
Subcellular location: Mitochondrion outer membrane; Cytoplasm
Subcellular location (Human Protein Atlas): Mitochondria; End piece; Principal piece
Pathways (Reactome):
Programmed Cell Death: Activation of BAD and translocation to mitochondria; BH3-only proteins associate with and inactivate anti-apoptotic BCL-2 members
Signal Transduction: AKT phosphorylates targets in the cytosol; NRAGE signals death through JNK
Disease: Constitutive Signaling by AKT1 E17K in Cancer
Gene Ontology:
Molecular function: lipid binding; phospholipid binding; protein binding; protein kinase binding; cysteine-type endopeptidase activator activity
Biological process: apoptotic process; cellular response to hypoxia; cellular response to mechanical stimulus; cellular response to nicotine; extrinsic apoptotic signaling pathway; intrinsic apoptotic signaling pathway; negative regulation of apoptotic process; pore complex assembly; positive regulation of apoptotic process; positive regulation of epithelial cell proliferation; positive regulation of proteolysis; positive regulation of release of cytochrome c from mitochondria; regulation of mitochondrial membrane permeability; ADP metabolic process; ATP metabolic process; glucose homeostasis; positive regulation of autophagy; positive regulation of insulin secretion; positive regulation of mitochondrial membrane potential; positive regulation of type B pancreatic cell development; type B pancreatic cell proliferation
Cellular component: BAD-BCL-2 complex; cytosol; mitochondrial outer membrane; mitochondrion; cytoplasm
Genetic constraint (gnomAD): Loss-of-function variants: 18 observed, 12.8 expected, observed/expected ratio (o/e) 1.41, 90% interval 0.96 to 1.89. The synonymous counts are far from expectation, so gnomAD's model fits this gene poorly and the ratio says little. Missense variants: 294 observed, 199.13 expected, observed/expected ratio (o/e) 1.48, 90% interval 1.34 to 1.63. Synonymous variants: 112 observed, 76.91 expected, observed/expected ratio (o/e) 1.46, 90% interval 1.25 to 1.7.
Homologues: Orthologues: chimpanzee BAD (100% identical), macaque BAD (96% identical), dog BAD (80% identical), pig BAD (79% identical), mouse Bad (76% identical), rat Bad (76% identical), Drosophila melanogaster CG15530 (25% identical).
Diseases named in the same sentence as BAD in open-access papers:
BAD is named in the same sentence as 132 diseases in open-access papers, as found by Europe PMC text mining. Sharing a sentence is not in itself a finding about the gene and the disease. The quoted sentences say what the papers report.
breast carcinoma (44 papers, 2010 to 2025). "Increased AKT activation and phosphorylation of BAD is associated with the adaptation of the breast cancer cell line MCF-7Ca cells to oestrogen deprivation." (PMID 38434478, 2024). "Remarkably, even though only limited data are available, in ER+ human breast cancers, higher BAD expression is associated with better disease-free survival." (PMID 37686282, 2023). "Our results clearly show that in breast cancer cells, ligand-activated intracellular AR upregulates BAD expression and causes its translocation in the nuclei." (PMID 37686282, 2023). "BAD, Bcl-2-associated death promoter, modulates breast cancer cell proliferation and tumor progression by regulating cell cycle progression, sensitizes breast cancer cells to chemotherapy." (PMID 36199443, 2022). "The Bcl-2 family member BAD (Bcl-2-associated death promoter) is a prognostic indicator for good clinical outcome of taxane-treated breast cancer patients." (PMID 31942016, 2020). "With the exception of BAD, a one-SNP model provided the best fit for the association of each gene with breast cancer." (PMID 27942580, 2016). "However, the protein, BAD, increased the susceptibility of breast cancer cells to docetaxel‐induced necroptosis." (PMID 40703196, 2025). "Additionally, the BAD encoding gene is downregulated in breast cancers from patients who developed metastasis, and its downregulation is statistically associated with positive lymph node status, advanced pathological stages, and tumor size." (PMID 37686282, 2023). "The MLKL inhibitor, necrosulfonaminde, significantly inhibited docetaxel‐mediated necroptosis in MDA‐MB‐231 breast cancer cells transfected with BAD, validating the role of BAD in the modulation of necroptosis." (PMID 40703196, 2025). "The overexpression of BAG-1 promotes phosphorylation at RAF driven BAD sites and inhibits apoptosis in breast cancer." (PMID 38434478, 2024). "In parallel, G-protein coupled oestrogen receptor 1 (GPER), can drive increased activity of PKA signalling which increases BAD phosphorylation and increases breast cancer cell survival." (PMID 38434478, 2024). "In ER+ breast cancer cells, BAD over-expression reduces cell growth and prevents cancer cell metastatic effusion by downregulating proteins that mediate epithelial-to-mesenchymal transition." (PMID 37686282, 2023). "Conversely, in primary ER+ breast cancers, higher BAD expression sensitizes cells to chemotherapy and is related to a significantly better disease-free survival." (PMID 37686282, 2023). "Our data indicate that, in ER+ breast cancer cells, the expression of the BH-3-only protein BAD is influenced by AR-dependent signaling, since its cellular levels appear to be significantly increased upon androgen administration." (PMID 37686282, 2023). "It has been previously demonstrated that nuclear BAD influences breast cancer cell-cycle progression by preventing cyclin D1 transcription." (PMID 37686282, 2023). "Low expression levels of AR and BAD are associated with decreased overall survival (OS) and relapse-free survival (RFS) in ER+ breast cancer, while their high levels appear to be protective, as Kaplan–Meier survival analyses show." (PMID 37686282, 2023). "Six hub genes (PSMC6, AURKB, CASP9, BAD, ZNF24, and SSX2IP) that were significantly associated with the prognosis of breast cancer." (PMID 36199443, 2022). "We then identified six hub genes (PSMC6, AURKB, CASP9, BAD, ZNF24, and SSX2IP) that were significantly associated with the prognosis of breast cancer." (PMID 36199443, 2022). "PRKACA belongs to the PKA signaling pathway; an elevated expression of PRKACA can regulate HER2-targeted therapy in breast cancer cells through the inactivation of the pro-apoptotic protein BAD." (PMID 35741587, 2022). "On the other hand, MST4 activated Ezrin-AKT signaling leads to the phosphorylation of BAD which in turn increases the survival and chemoresistance of breast cancer cells." (PMID 36552828, 2022).
breast carcinoma (continued). "BAD stimulates cell cycle progression leading to increased breast cancer cell number and tumor growth." (PMID 31942016, 2020). "BAD modulates breast cancer cell proliferation and tumor progression by regulating cell cycle progression." (PMID 31942016, 2020). "We also demonstrated that BAD expression in human breast carcinoma cells generated larger tumors in mouse xenograft models." (PMID 31942016, 2020). "It has recently been shown that stimulation with tamoxifen, activates GPER-1, improving breast cancer stem cells viability and stemness and BAD phosphorylation, event that seems to be an alternative survival mechanism for these cells." (PMID 33117280, 2020). "Understanding the mechanism of docetaxel cell death will aid in understanding BAD’s function as a prognostic biomarker in breast cancer." (PMID 31942016, 2020). "To study the structure/function relationship of BAD in docetaxel-treated breast cancer cells, we utilized MDA-MB-231 cells stably expressing ectopic BAD7." (PMID 31942016, 2020). "Here we showed that BAD increased cell growth in breast cancer cells through two distinct mechanisms." (PMID 30635657, 2019). "We found that BAD regulated breast cancer cell growth by concurrent phosphorylation dependent and independent pathways." (PMID 30635657, 2019). "In breast cancer cells of this study, however, BAD-mediated changes in glucose metabolism were downstream of glycolytic hexokinase and independent of phosphorylation status." (PMID 30635657, 2019). "Immunofluorescence was used to compare the expression levels of phosphorylated BAD [pBAD (serine-112, -136 and -155)] in immortalized normal and invasive ovarian, colon and breast cancer cells." (PMID 25653146, 2015). "The normal breast samples (n=143) had a mean BAD-mediated apoptotic pathway expression score of 2.721 vs. a score of −0.799 for the breast cancer samples (n=42; P<0.001)." (PMID 25653146, 2015). "Their expression is often disturbed in malignant tissue, and reduced expression of BAD and BAX is associated with poor prognosis in breast cancer." (PMID 21542898, 2011). "Detecting the expression of the BCL-2 protein expression level, in particular the combined detection of the expression of BCL-2 and BAD as well as ER and PR were helpful in the prognosis of breast carcinoma." (PMID 20691103, 2010). "The expression of BCL-2, BAD genes in young human breast carcinoma tissues were lower than that in menopause human breast carcinoma tissues (P < 0.05)." (PMID 20691103, 2010). "Detection of the BCL-2 protein expression level, particularly, combined with the detection of the expression of BCL-2 and BAD as well as ER and PR were helpful in confirming the prognosis of breast carcinoma." (PMID 20691103, 2010). "In our study the breast cancer cells with BAD expression positive were more sensitivity to EADM and NVB than the negative ones." (PMID 20691103, 2010). "In this study we find that the expression of BCL-2, BAD in tissues of breast carcinoma are significantly lower than tissues of normal breast and tissues of breast fibroma." (PMID 20691103, 2010). "Tumor COX-2, HER2 and estrogen receptor α (ER) expression and phosphorylation of Akt, BAD, and caspase-9 were analyzed immunohistochemically in 248 cases of breast cancer." (PMID 21078168, 2010). "In this study we found that the expression rates of BCL-2 and BAD in tissues of youth breast carcinoma were significantly lower than in the tissues of menopause breast carcinoma." (PMID 20691103, 2010). "Immunohistochemical technique was used to detect the expression of BCL-2, BAD in 10 normal breast tissues, 10 breast fibroadenoma tissues, 40 youth human breast carcinoma tissues, 40 menopause human breast carcinoma tissues." (PMID 20691103, 2010).
breast carcinoma (continued). "The therapeutic significance of PRKACA expression in cancer had previously been suggested by a breast cancer study, which showed that PRKACA mediates resistance to anti-HER2 therapy in breast cancer cell lines via inactivation of BAD and Bcl2-associated death promoter." (PMID 39458904, 2024). "In the present research, a significantly increased expression of BAD gene was observed in both breast cancer cell lines and a significantly increased expression of BID gene in the MDA-MB-231 cell line under the influence of digested juice from young beetroot shoots." (PMID 37108053, 2023). "The reported androgen-dependent nuclear localization of BAD might further explain the protective action exerted by androgens against the growth of breast cancer cells." (PMID 37686282, 2023). "However, the mechanism(s) linking BAD to the pathobiology of human breast cancer is (are) yet to be resolved." (PMID 37686282, 2023). "To better elucidate the role of AR and BAD cooperation, we investigated if our findings may have an impact on the outcome of ER+ breast cancer patients." (PMID 37686282, 2023). "To further clarify the interaction between DEGs, we screened fifteen hub genes by constructing the PPI network, among which the expression of PSMC6, AURKB, CASP9, BAD, ZNF24, and SSX2IP was associated with OS in breast cancer patients, which attracted our attention." (PMID 36199443, 2022). "Thus, forced expression of a BAD mutant with a phosphomimic at S118 can drive breast cancer cell and tumor growth." (PMID 30635657, 2019). "We showed that in primary breast cancer, elevated BAD levels correlated with a 3.7-fold increased likelihood of patient survival and was a better prognostic indicator than tumor grade, HER2 or estrogen receptor suggesting a causal contribution to tumor suppression." (PMID 30635657, 2019). "Related experiments in breast cancer found that phosphorylation of BAD at S118 stimulates the survival pathway, which in turn phosphorylates BAD at S99, resulting in binding to the 14-3-3 protein, thereby affecting the proliferation of breast cancer tumor cells." (PMID 31496919, 2019). "In summary, we have identified a novel mechanism of BAD-mediated growth in breast cancer." (PMID 30635657, 2019). "In vivo, BAD phosphorylation was detected in CSCs of 83% breast cancer biopsies." (PMID 29385093, 2018). "Moreover, a role for MMP10 has been proposed in MCF-7 breast cancer cells via regulation of the BAD protein." (PMID 27351228, 2016). "Moreover, BAD have been shown to be prognostic biomarkers for colon cancer, ovarian cancer, and breast cancer patients." (PMID 23725574, 2013). "BAD−/− mammary cancer cells are resistant to gefitinib-therapy in the study by Gilmore." (PMID 23725574, 2013). "Moreover, TIMP-1 silencing by antisense technology blocked NO-induced PI3k/Akt/BAD phosphorylation in cultured MDA-MB-231 human breast cancer cells." (PMID 22957045, 2012). "The expression of BCL-2 and BAD can be used as prognosis factors of breast cancer." (PMID 20691103, 2010). "The expression rates of BCL-2 in youth and menopause human breast carcinoma were 47.5% and 75%(P < 0.05), The expression rates of BAD in youth and menopause human breast carcinoma were 30% and 65%, the differences were statistically significant(P < 0.05) (P < 0.05)." (PMID 20691103, 2010). "In our study, immunohistochemistry was used to detect the expression of BCL-2 and BAD in breast carcinoma, in addition, to analyze the relationship between the expression of the two genes and the expression of ER, PR histologic grade, clinical stage and the lymph node metastasis." (PMID 20691103, 2010). "Thus, the role of BAD in breast cancer and how this relates to clinical outcome is unclear." (PMID 30635657, 2019). "Therefore, we examined whether BAD modulated cellular metabolism, and consequently, survival and proliferation of breast cancer cells." (PMID 30635657, 2019).
breast carcinoma (continued). "Similar patterns of BAD cellular levels and localization were also observed in ER+/AR+ T47D and ZR75, as well as in ER−/AR+ SKBR3 breast cancer cells." (PMID 37686282, 2023). "Next, ASSIGN was used to estimate the activation of each GFRN member (AKT, BAD, EGFR, HER2, IGF1R, KRAS (G12V), and RAF1) in 1119 breast cancer patient samples from TCGA and 55 samples from the ICBP panel of breast cancer cell lines." (PMID 28446242, 2017). "BAIAP2 was associated with overall and ER+ breast cancer; CALM2 with overall breast cancer; CSNK2A1 with ER+ breast cancer; and BRAF, BAD, and MAPK3 with ER− breast cancer." (PMID 27942580, 2016). "The most significant gene associations (P⩽0.01) were BAIAP2 and CALM2 for overall breast cancer; BAIAP2 and CSNK2A1 for ER+ breast cancer; and BRAF, BAD, and MAPK3 for ER− breast cancer." (PMID 27942580, 2016). "In a previous study of inflammation and breast cancer, we had found a positive correlation between COX-2 expression and increased phosphorylation of Akt, caspase-9 and BAD in breast tumors." (PMID 21078168, 2010). "In breast cancer histologic grade I to III the expression of BCL-2 assumed the decreasing tendency, the differences had significant difference, the expresses of BAD during this process also gradually reduced." (PMID 20691103, 2010). "The breast cancer cells in which BCL-2 and BAD are all positive are more chemosensitive to NVB than the BCL-2(+)BAD(-)ones(P < 0.05)." (PMID 20691103, 2010). "Compared to other breast cancer cell lines, MDA-MB-231 exhibit the highest expression of β-adrenoreceptors and treating these cells with ADR confers resistance to apoptosis through BAD protein inhibition." (PMID 38962320, 2024). "time point suggesting that the cell death induced by CHCP treatment on breast cancer cells does not involve BAD mRNA expression." (PMID 35260587, 2022). "Surprisingly, BAD did not sensitize breast cancer cells to apoptosis but instead stimulated progression through the cell cycle." (PMID 30635657, 2019). "A study on breast cancer cells suggested that E2 is an anti-apoptotic agent whose response is mediated by non-genomic cytoplasmic signal networks that converge on BAD, in turn regulating changes in the mitochondrial membrane potential." (PMID 30283401, 2018). "In breast cancer cell MCF7, cell growth was also inhibited by BAD overexpression." (PMID 23725574, 2013). "This may guide future studies examining whether BAD predicts patient response to taxane therapy and may suggest non-taxane chemotherapy for breast cancer patients with low BAD levels." (PMID 31942016, 2020). "The positive rates of BCL-2 and BAD were all showed declining trend in the clinical TNM stage from I to IV of youth and menopause breast cancer tissues, but, the difference has no significance (P = NS)." (PMID 20691103, 2010). "The expression of BCL-2 and BAD gene in breast carcinoma tissues were indicated by brown granules, mainly distributes in the cytoplasma, and non-uniform; The positive expression of BCL-2 and BAD in breast carcinoma." (PMID 20691103, 2010).